BCL2 (BCL2 apoptosis regulator)
Diseases named in the same sentence as BCL2 in open-access papers (continued):
Sharing a sentence is not in itself a finding about the gene and the disease.
breast carcinoma (continued). "In addition, γ-tocotrienol also induced typical morphological characteristics of apoptosis in MDA-MB-231 human breast cancer cells, with no change of bax and bcl-2 expression and absence of poly-(ADP-ribose)-polymerase cleavage." (PMID 23469066, 2013). "In addition, we identified ER, Bcl-2, Myb, and GATA3 at the center of the good prognostic gene cluster, which matched perfectly with the known clinical and pathologic roles of these molecules in breast cancer." (PMID 23029298, 2012). "Thus, combining Bcl-2/Bcl-xL and Mcl-1 inhibition by ABT-737 and GSIXII, respectively, should restore apoptosis sensitivity efficiently and affect survival maintenance, in breast cancer cells." (PMID 22703841, 2012). "The aim of this study was to use a cohort of breast cancer cases, from the Sheffield Breast Cancer Study (SBCS) to determine whether there is a relationship between the promoter SNP rs2279115 and tumour protein levels of BCL2, and whether this corresponds to any differences in patient survival." (PMID 23961365, 2012). "The obtained data indicated that antimitotic effect of D-glucuronyl C5-epimerase in human breast cancer cells in vitro probably is realized mainly via the activation of tumour suppressor genes р53, BRCA1, SYK and E2F1 and change of a balance of pro- and anti-apoptotic factors BCL2, NFKB1 and TNF." (PMID 20723247, 2010). "This ‘paradoxical’ favourable prognostic effect of BCL2 in breast cancer could be related to its non-apoptotic functions." (PMID 20664598, 2010). "The prospective analysis in over 11 000 women with early-stage breast cancer reported here demonstrates for the first time the robust prognostic significance of BCL2 protein expression independent of ER, as well as all the other traditional prognostic markers used in clinical practice." (PMID 20664598, 2010). "In the drug sensitivity test in vitro of breast cancer cells of 4 kinds of chemotherapeutic agents in 0.1 × PPC, the chemosensitivity and the expression level of BCL-2 are related, the chemosensitivity of the BCL-2(-) tumor cells was higher than the BCL-2(+) tumor cells(Table." (PMID 20691103, 2010). "The authors did not observe any apoptosis effect in breast cancer cells upon Bcl-2 silencing." (PMID 20863366, 2010). "Furthermore, BER suppresses Akt and nuclear factor κB signaling by reducing the phosphorylation of c-Met and Akt, and inhibiting their downstream targets such as nuclear factor κB p-65, Bcl-2/Bax, osteopontin, VEGF, MMP-9 and MMP-2 on protein and/or mRNA levels in breast cancer cells." (PMID 19796390, 2009). "Evaluation of Bcl-2 and Bag-1 expression in breast cancer may identify a subset of patients with a favorable prognosis, who might not benefit from chemotherapy or who might benefit from Bcl-2 targeting agents in addition to antihormonal therapy." (PMID 18430249, 2008). "The meta-analysis strongly supports the prognostic role of BCL2 as assessed by immunohistochemistry in breast cancer and shows that this effect is independent of lymph node status, tumour size and tumour grade as well as a range of other biological variables on multi-variate analysis." (PMID 18510726, 2008). "Three categories had median P values below 0.001 (FDR = ~0): breast cancer estrogen signaling; MSigDB's set of ER-upregulated genes identified by Frasor and coworkers; and drug resistance and metabolism, which contains ESR1, BCL2, AR and ER's co-regulator ERBB4." (PMID 17845722, 2007). "The ability of WT1–ZF to reduce/block the expression of genes such as c-myc, Bcl-2, AREG and WT1 itself, genes important for the survival and proliferation of breast cancer cells, raised the possibility that WT1–ZF could impair the growth of breast cancer cells." (PMID 17634147, 2007).
breast carcinoma (continued). "Multivariate analyses determined the Bcl-2 protein expression to be an independently significant prognostic factor for breast cancer, while other studies, as well as the present study, determined Bcl-2 protein expression to not be an independently significant prognostic factor." (PMID 16839413, 2006). "This marked difference may explain the different prognostic values of Bcl-2 compared to Bcl-XL expression in human breast cancer samples independent of the presence of the estrogen receptor." (PMID 16928273, 2006). "In addition to the prototypical 36 kDa BAG-1 isoform, breast cancer cells expressed higher molecular weight isoforms and, in contrast to BCL-2, BAG-1 expression was independent of oestrogens." (PMID 10576663, 1999). "Through rank correlation analysis, Study has found a negative correlation between BCL-2 expression and chemotherapy sensitivity of breast cancer, suggesting that BCL-2 may make breast cancer cells resistant to chemotherapy drugs through its anti-apoptotic function." (PMID 40104496, 2025). "Additionally, in models of MYC-driven breast cancer, the combined use of metformin with venetoclax or navitoclax suppressed tumor cell growth effectively and induced immune infiltration into tumors, which adds new insight into the strategy of cotargeting AMPK and BCL-2 to enhance synergy." (PMID 37894324, 2023). "Therefore, in MCF-7 breast cancer cells, the simultaneous treatment of paclitaxel with curcumin exhibited synergistic growth inhibition through EGFR signaling modulation and induced significant apoptosis as demonstrated by bax increase and bcl-2 protein expression decrease." (PMID 36675194, 2023). "The RelA subunit of NF-κB is reported to be activated in breast cancer cell lines, whereas breast tumours are shown to exhibit an absence or low level of nuclear RelA, in contrast to activated c-Rel, NF-κB1 and NF-κB2 along with bcl2 expression, as compared to nontumorigenic adjacent tissue." (PMID 36899924, 2023). "Moreover, the current study provided the first evidence of MAO-A involvement in the regulation of several genes in human breast cancer; modulation of MAO-A, VEGF, and Bcl-2 genes may indicate the multisignaling pathways in which MAO-A is involved in the cancer cellular compartment." (PMID 37841082, 2023). "The collective findings on this novel Bcl-2 BH4 antagonist suggest that CYD0281 may act as a powerful pharmacological tool for further elucidating the functions of Bcl-2 and its BH domains, and also serve as a potential therapeutic drug candidate for targeting neovascularization in breast cancer." (PMID 37237269, 2023). "A previous study demonstrated that the suppression of Bcl-2 by siRNA knockdown could induce ACD but not apoptosis in breast cancer cells, so the induction of autophagy together with Bcl-2 suppression could offer a better option for cell death induction for cancer treatment." (PMID 33805467, 2021). "Collectively, we here demonstrate that BCL2 inhibitors decrease mitochondrial bioenergetics and that the targeting of glycolysis, mitochondrial metabolism and cell death signalling by a combination of BCL-2 and glycolysis inhibitors could potentially benefit both ER+ and TNBC breast cancer subtypes." (PMID 29899841, 2018). "Moreover, re-expression of both Bcl-2 and Cyclin E1 almost fully restored tamoxifen-resistance when miR-15a/16 mimics were co-transfected, suggesting Bcl-2 and Cyclin E1 work synergistically to confer tamoxifen resistance in breast cancer cells, but not being redundant to each other." (PMID 26397135, 2015). "However, whether these estradiol-repressible miRNAs coordinately control cell proliferation and survival by targeting bcl-2, cyclin D1 and survivin at the post-transcriptional level in breast cancer cells is not fully investigated." (PMID 22260523, 2012).
breast carcinoma (continued). "As GSIXII induced the expression of proapoptotic Noxa, which inhibits the survival activity of Mcl-1, we inferred that its combination with the BH3 mimetic ABT-737, which targets Bcl-2 and Bcl-xL but not Mcl-1, might improve apoptosis induction in breast cancer cells." (PMID 22703841, 2012). "However, it has not yet been determined whether bcl-2 or bcl-2 related genes play any role in the development of breast cancer." (PMID 20441573, 2010). "Here, we revealed that BCL2, BCL2A1, BCL2L2, and MCL1 but not BCL2L1 were overexpressed in estrogen receptor (ER)-positive breast cancer cells and clinical biopsies." (PMID 36853387, 2023). "Although the role of BCL-2, BAX, and HER2/neu is established in breast cancer pathogenesis, the exact molecular mechanism is still not clear." (PMID 33708254, 2021). "A total of 70% of breast cancers had a negative correlation between levels of PARK2 protein and BCL-2 protein according to The Human Protein Atlas database." (PMID 32929329, 2020). "First, β2M activates SGK1 signaling and upregulates Bcl-2 expression, and do not affect HER2, HIF-1α, VEGF, and ERK signaling in ER+ breast cancer cells with HER2−." (PMID 30866857, 2019). "In this work, we demonstrated that single agent treatment with the selective BCL2 inhibitors Venetoclax and WEHI-539 at therapeutically relevant concentrations decreases mitochondrial ATP production in breast cancer cells in the absence of cell death." (PMID 29899841, 2018). "Consistently with a previous report indicating that γ-tocotrienol induced a mitochondrial disruption pathway without affecting Bax/Bcl-2 expression in human breast cancer MDA-MB-231 cells, the Bax/Bcl2 ratio was not affected by any of the treatments." (PMID 29156559, 2017). "Our observations also evoke BCL-2/HRAS interactions and their reported effects on de-differentiation of luminal breast cancer cells, by mechanisms that have not been totally described yet29." (PMID 29066722, 2017). "Both lung and breast cancer cells showed higher levels of COX1, ND1, ATPase 6/8 and CYTB after bcl-2 overexpression, but not a significant modulation of ND3, ND5 and ND6 transcripts." (PMID 26866271, 2016). "The authors have described G2/M arrest, activation of caspase-9 and caspase-3/7 (but not caspase-8) in the metastatic breast cancer cell line MDA-MB-231 by boldine, which also down-regulates Bcl-2 and heat shock protein 70 and up-regulates Bax." (PMID 25719742, 2015). "Fourth, β2-M siRNAs significantly inhibited Bcl-2 mRNA expression, but did not inhibit ER, PR and HER-2 mRNA expression in breast cancer cells with ER+, PR+ and HER-2− status." (PMID 25292288, 2014). "We did not observe significant dephosphorylation of Bcl2 in any of the cell lines, suggesting that upregulation of PP2A in breast cancer cells exclusively dephosphorylates Bad ser136 without significantly affecting other Bcl family members." (PMID 23886499, 2013). "The positive rates of BCL-2 and BAD were all showed declining trend in the clinical TNM stage from I to IV of youth and menopause breast cancer tissues, but, the difference has no significance (P = NS)." (PMID 20691103, 2010). "BECN1 knockdown, in combination with BCL2+BCL-W co-inhibition, inhibited autophagy, restored ICI sensitivity, and increased apoptosis (but not necrosis) in ICI treated antiestrogen-resistant breast cancer cells." (PMID 20062536, 2010). "The molecular mechanisms of mitochondrial dysfunction in breast cancer are not entirely understood, and they might involve crosstalk between GCR, SGK1, and Bcl-2 via chronic stress and apoptosis pathways." (PMID 37370761, 2023).
breast carcinoma (continued). "In this case, the involvement of JMJD3 is no longer needed, which highlights the existence of non-genomic pathways in the regulation of the BCL2 gene by EZH2, whereas JMJD3 is able to positively regulate BCL2 expression in a genomic way in non-resistant breast cancer cell lines." (PMID 33478063, 2021). "Based on data demonstrating a difference in the dependence of CAFs on BCL-2 vs. MCL-1 for survival, studies have shown that CAFs in human breast cancer are sensitive to inhibitors targeting MCL-1 (A-1210477 and S63845) but not to those targeting BCL-2/BCL-XL (ABT-737 and navitoclax)." (PMID 33114328, 2020). "β2M may promote tumor survival through the SGK1/Bcl-2 signaling pathway in ER+ breast cancer with HER2− and have no regulatory effects on ER− breast cancer with HER2−." (PMID 30866857, 2019). "This could also explain why in our conditions Bcl-2 was not decreased upon CAI, as was the case in the MCF-7 breast cancer cell line." (PMID 30338034, 2018). "This small molecule has recently been found to target breast cancer cells without any apparent effect on normal breast cells, a specificity that could reflect the high levels of NAF-1 and BCL-2 in these cells." (PMID 26621032, 2016). "Furthermore, according The Cancer Genome Atlas (TCGA) genetic amplification of Bcl2 and Bcl2l1 (encoding Bcl-xL) occurs in less than 3% of luminal B and TNBC cases, implying that BH3-mimetic targeting of Bcl-2 and Bcl-xL may not be beneficial in most breast cancer subtypes." (PMID 25784482, 2015). "Therefore, BRD7 may inhibit the malignant progression of breast cancer and improve the chemotherapy sensitivity of PTX by negatively regulating the activity of the YB1/Bcl-2 transcription axis, which needs further investigation." (PMID 41315221, 2025). "However, none of the investigated apoptosis-related proteins (Bcl2, Bax, Bcl-xl, Bag1, FAS, FASL) could be helpful in predicting the response to drug treatment for breast cancer." (PMID 35163777, 2022). "First, in breast cancer, there was no induction of apoptosis through the intrinsic pathway because the mitochondrial membrane potential was not reduced in human epidermal growth factor receptor 2(HER-2)-expressing breast cancer BT-474 cells without the effect of Bcl-2 or BAX." (PMID 36142874, 2022). "Consequently, β2M may promote tumor survival through the SGK1/Bcl-2 signaling pathway in ER+ breast cancer with HER2− and have no regulatory effects in ER− breast cancer with HER2−." (PMID 30866857, 2019). "β2M has a different molecular regulatory mechanism between ER+ and ER− breast cancer with HER2−, and it may promote tumor survival through the SGK1/Bcl-2 signaling pathway in ER+ breast cancer with HER2− and has no regulatory effects on ER− breast cancer with HER2−." (PMID 30866857, 2019). "However, the expression levels of cyclin D1 and c-myc, but not those of Bcl-2 and Mcl-1, were increased upon PIAS3 overexpression in MCF7 cells, suggesting that the PIAS3-mediated effects on ER-positive breast cancer cells may be promoter-specific or ER-related." (PMID 26768588, 2016).
lymphoma (794 papers, 1992 to 2026). A malignant (clonal) proliferation of B- lymphocytes or T- lymphocytes which involves the lymph nodes, bone marrow and/or extranodal sites. "We initially evaluated a T58I variant of MYC in combination with BCL2, as this combination has been previously used in lymphoma modelling." (PMID 40721291, 2025). "BCL2 overexpression is associated with an increased risk of lymphoma, whereas BCL6 plays a crucial role in maintaining germinal center B cells." (PMID 40563566, 2025). "Selinexor significantly increased CD20 expression on the surface of B-NHL cells, inhibited the proliferation of double-hit (Bcl-2 and C-Myc mutation-positive) lymphoma cell lines, and exerted a remarkable synergistic effect when combined with CHOP." (PMID 40375183, 2025). "Researchers found that a translocation in follicular lymphoma involving chromosomes 14 and 18 positioned BCL-2 near a high-expression region, causing overproduction of lymphoma cells." (PMID 40204952, 2025). "Beyond VEGF, SRPK1 inhibition alters the splicing of MCL1/BIN1/BCL2 to produce pro-apoptotic isoforms in cholangiocarcinoma and causes stress-associated cell death in lymphoma." (PMID 41551143, 2025). "Bcl-2 overexpression is commonly associated with resistance to apoptosis and poor prognosis in lymphomas." (PMID 41346921, 2025). "Both CD30 (associated with activated T-cells and certain lymphoma types) and Bcl-2 (an anti-apoptotic marker) are moderately expressed." (PMID 40981339, 2025). "In the subset of patients who did not receive systemic treatment initially, i.e., those observed or treated only with local radiation, the presence of prevalent nonsynonymous BCL2 mutations was also associated with earlier time to lymphoma-associated death." (PMID 37193683, 2023). "In other words, the BCL2-CA genotype increased the risk of lymphoma by 1.44 times (95% CI = 1.089–1.91) compared to the controls." (PMID 36831357, 2023). "BCL2-CA and BCL2-CC + AA genotypes were associated with a lower risk of lymphoma (OR = 0.48, 95% CI = 0.277–8.04; RR = 0.70, 95% CI = 0.53–0.92)." (PMID 36831357, 2023). "In contrast, the EZB-MYC+ subtype, which is associated with concurrent MYC and BCL2 rearrangements (so-called “double-hit” lymphomas [DHL]), exhibited a relatively lower GC TFH signature." (PMID 36765793, 2023). "Nonetheless, beyond 10 years the rate of lymphoma-associated death even in this rituximab-treated subgroup increased if prevalent nonsynonymous BCL2 mutations were present at diagnosis." (PMID 37193683, 2023). "Forty-nine variations identified using whole exome sequencing demonstrated a mutational burden on the BCL2 gene’s role in lymphoma genesis." (PMID 36831357, 2023). "EZH2 mutations are enriched in GCB-DLBCL and are the characteristic gene aberrations of EZB-type lymphoma, which harbors both mutations and BCL2 aberrations." (PMID 36765793, 2023). "In multivariate analysis, the codominant model’s BCL2-CA genotype was highly linked to an increased susceptibility to lymphoma." (PMID 36831357, 2023). "Ezh2 GOF mutation cooperates with BCL2 deregulation (VavP-BCL2, Cγ1cre Ezh2Y641F/wt) to increase the frequency of lymphomas with features of GCB-DLBCL." (PMID 38022603, 2023). "The findings revealed that BCL2 mutations are linked to increased activation-induced cytidine deaminase production, altered antiapoptotic BCL2 function, and a higher probability of lymphoma transformation and death." (PMID 36831357, 2023). "BCL7A, IGLL5, and BCL2 are likely false positives as they were mutated primarily in lymphomas, where they are known targets of local AID-mediated somatic hypermutation." (PMID 36396655, 2022).